INS (insulin)
Diseases named in the same sentence as INS in open-access papers (continued):
Sharing a sentence is not in itself a finding about the gene and the disease.
diabetes (continued). "For example, it has been shown that insulin and/or insulin-like growth factors and their coordinate signaling, which is defective in insulin-resistant states such as diabetes, impact collagen metabolism." (PMID 28824924, 2017). "The thiazolidinedione troglitazone is a PPARγ agonist used as an insulin sensitizer for treatment of diabetes that also exhibits weak affinity to PPARα." (PMID 28137721, 2017). "Pathogenetic study of these tissues contributes to understanding the etiology of impaired insulin action and diabetes development." (PMID 28117714, 2017). "Patients who developed/progressed DR had longer diabetes duration, used more frequently insulin, and had greater prevalences of other microvascular complications than patients who did not developed/progressed DR." (PMID 28687808, 2017). "In particular, recent advances in directing hPSCs to pancreatic cell phenotypes, especially insulin-producing β-cells, have sparked hope for cell therapies for diabetes." (PMID 28680477, 2017). "For example, many participants with diabetes in the control arm used insulin and likely made insulin-titration decisions based on blood glucose results." (PMID 28698169, 2017). "This review summarizes the role of tissue-specific LRP1 in insulin signaling and its potential role as a link between lipoprotein and glucose metabolism in diabetes." (PMID 28584820, 2017). "Diabetes mellitus is a metabolic disease with an impaired carbo-hydrate turnover, characterized by a decreased rate of insulin secretion and reduced insulin sensitivity of cells expressing insulin receptors." (PMID 29065463, 2017). "Those animal models display an increase in β-cell proliferation, insulin secretion, and sensitivity that protect them from induced obesity and diabetes." (PMID 28695134, 2017). "In animals and humans with diabetes, increased insulin levels and abnormal glucose metabolism triggers aberrant circadian rhythms." (PMID 28764741, 2017). "The present research is absolutely important for the understanding of how systemic stress can regulate insulin level/sensitivity via the action of NO and attribute to the occurrence and severity diabetes." (PMID 28811499, 2017). "Type 2 diabetes mellitus (T2DM) results from the body’s ineffective use of insulin and it accounts for the vast majority of people with diabetes around the world." (PMID 29233152, 2017). "According to the World Health Organization (WHO), diabetes is a chronic disease that occurs as a result of the pancreas’s inability to produce enough insulin or ineffective use of insulin produced by the body." (PMID 28981464, 2017). "In this trial, we aimed to assess the effects of dapagliflozin, one of the SGLT2 inhibitors, on glucose fluctuation in patients with type 2 diabetes mellitus on insulin using a prospective, randomized parallel-group comparison study design." (PMID 28725273, 2017). "In specific, the diabetes group had a significantly different (higher) glucose levels compared to controls (p< 0.0001), and diabetes with insulin had also significant difference (higher) levels of glucose compared to controls (p = 0.0003)." (PMID 29121074, 2017). "The absence of any clear adverse or beneficial effect of 100 % fruit juice on markers of diabetes in the present meta-analysis of available RCT suggests a largely neutral role of 100 % fruit juice on glucose–insulin homeostasis." (PMID 29299307, 2017). "STZ-induced diabetes is characterized by pancreatic β-cell damage and insufficient insulin synthesis, which are all related to oxyradicals." (PMID 28662169, 2017). "Type 2 diabetes mellitus, which affects approximately 11% of adults in the U.S. and 8% worldwide, is resulted from a progressive decline in insulin action and the reduced response of β-cells to insulin." (PMID 28676080, 2017). "This way of data-based modelling leads to a result that can be applied in the closed-loop control of the blood glucose level by an external input of insulin in case of diabetes." (PMID 28060898, 2017).
diabetes (continued). "We observed different trajectories of plasma glucose, insulin sensitivity and secretion prior to diabetes diagnosis in South Asian and white individuals." (PMID 28409212, 2017). "These progress to hyperglycemia/pre-diabetes and frank diabetes with decreasing insulin levels as they age." (PMID 28640857, 2017). "In our systematic review, we evaluated the safety and efficiency when SGLT2 inhibitor was used as insulin add-on therapy in diabetes mellitus." (PMID 28538386, 2017). "This optogenetic system with modulation of cAMP and insulin release can be employed for the study of β-cell function and for enabling new therapeutic modalities for diabetes." (PMID 28839233, 2017). "The two groups were of similar age, diabetes duration, and had similar BP, HbA1c level, insulin regimen, prevalence of microvascular complications, educational level and computer familiarity." (PMID 28280899, 2017). "These included hypertension, arteriosclerotic heart disease, CV renal disease, coronary heart disease, diabetes, insulin or glucose levels, metabolic syndrome, medication for heart diseases, medication for hypertension and uric acid level." (PMID 28851330, 2017). "The role of PCSK9 in glycaemic control and diabetes will not be discussed, because the most important findings are already summarized in section “Insulin signaling, diabetes and PCSK9 expression”." (PMID 28439730, 2017). "Although our patient exclusion criteria excluded those with diabetes and those being treated for insulin resistance, it is possible some of our obese patients were insulin resistant." (PMID 28740130, 2017). "Most patients with diabetes (~90%) have type 2 disease, characterized by reduced insulin secretion and insulin resistance with diagnosis in late adulthood, while patients with type 1 diabetes are insulin deficient." (PMID 28076434, 2017). "In the group of patients with diabetes five were treated with metformin only and two with metformin and insulin." (PMID 28928716, 2017). "This convention has been challenged by the emergence of short and ultrashort-acting insulin analogues, which has now become much more familiar to clinicians than regular human insulin in general diabetes management." (PMID 28659865, 2017). "A 62-year-old man with type 2 diabetes mellitus, who had been on insulin therapy for the past 20 years, was found to have subcutaneous mass formation in the abdomen during a workup of worsened glycemic control." (PMID 29403667, 2017). "Thakker have reported 11 patients with RMS and type A insulin resistance who were diagnosed with diabetes at presentation and treated with high-dose insulin and insulin-sensitizing drugs." (PMID 28663160, 2017). "The patient developed diabetes mellitus with relatively preserved insulin secretion while on ART, and the discontinuation of zidovudine improved his hyperglycemia to a level where he did not require diabetes medications." (PMID 28610599, 2017). "Progression from normoglycemia to pre-diabetes is thought to be driven by insulin resistance, while progression to type 2 DM and need for insulin therapy is further affected by beta cell dysfunction." (PMID 28258520, 2017). "Dysregulation of the insulin/PI3K/Akt pathway is implicated in several human diseases including cancer, diabetes, cardiovascular diseases and neurological diseases." (PMID 28861129, 2017). "The prescription patterns were similar among those with insulin-dependent and non-insulin-dependent diabetes mellitus, in that people with ID were more likely to be prescribed combination drugs and sulfonylureas." (PMID 29169334, 2017). "Previous studies have shown that the duration of diabetes is related to the development of FS after controlling for insulin use (odds ratio: 1.85 for the duration of more than 10 years of use compared to those with less than 5 years of use)." (PMID 29018641, 2017).
diabetes (continued). "A recent meta-analysis concluded that CABG was associated with a significantly lower overall mortality rate and with less cerebrovascular and major adverse cardiovascular events than PCI among insulin-treated type 2 diabetes mellitus patients." (PMID 29017514, 2017). "It is also important to note that for some prenatal characteristics, e.g., for insulin-treated diabetes in a previous pregnancy, maternal Sjögren’s syndrome, less than ten pairs of women and neonates were present in the risk group." (PMID 28503212, 2017). "Comprehensive and effective control of diabetes, as well as the use of insulin, requires further study to develop additional treatment options." (PMID 28758131, 2017). "In August 2014, the US FDA granted tentative approval for Eli Lilly’s Basaglar®, a recombinantly produced insulin glargine analog for treating diabetes." (PMID 27446593, 2017). "A woman with multiple illnesses – of which one is diabetes – requires high-dose insulin injections several times a day." (PMID 28836981, 2017). "Type 2 diabetes mellitus is a progressive metabolic disorder, characterized by hyperglycemia and insulin resistance in peripheral tissue." (PMID 29203903, 2017). "These mice displayed defective insulin secretion in response to glucose and overt diabetes starting at the age of 4 weeks." (PMID 28598424, 2017). "Diabetes mellitus is a chronic metabolic disease in which people cannot properly regulate their blood glucose levels due to inadequate insulin production and/or insulin resistance." (PMID 28272368, 2017). "Animals with diabetes had higher fasting blood glucose (9.9 ± 0.6 mmol/l vs. 4.6 ± 0.3 mmol/l, p < 0.001) and higher insulin concentrations (7.7 ± 1.6 μIU/ml vs. 0.7 ± 0.3 μIU/ml, p < 0.001) than animals without diabetes." (PMID 29121919, 2017). "In contrast to glucose, fatty acid uptake across the plasma membrane is insulin independent, allowing an augmentation of the delivery of circulating fatty acids to the myocytes for oxidation in diabetes." (PMID 28933367, 2017). "Although hypoglycemia is a common complication of insulin treatment in diabetes, very few studies have evaluated the frequency and predictors of self-reported hypoglycemia on an ambulatory basis, especially in insulin-treated type 2 diabetes." (PMID 28913365, 2017). "The present work unravels the insulin-mimetic effect and the antioxidant property exerted by steviol glycosides, suggesting their potential beneficial role in the cotreatment of diabetes and in health maintenance." (PMID 28947927, 2017). "In about 20% of insulin resistant individuals, beta cells eventually fail to deliver a sufficient amount of insulin, resulting in the development of glucose intolerance and ultimately fasting hyperglycemia and overt diabetes." (PMID 28270834, 2017). "Pertaining towards anti diabetic agents taken, 78 (28.89%) were used insulin alone, 25 (9.26%) were used insulin and oral anti diabetic agents together and the rest 167(61.85%) were used oral anti diabetic agents alone to manage their diabetes." (PMID 28253261, 2017). "The results suggested that both genes are related to insulin response, and their abnormal expression levels in the blood indicate the progression of diabetes." (PMID 28117714, 2017). "Defects in insulin bioavailability or impaired insulin receptor signaling lead to different pathological conditions such as diabetes (3, –, 5), cancers (6, –, 8), and Alzheimer's disease." (PMID 28348075, 2017). "Other independent associations included previously reported measures such as age, diabetes duration, and insulin treatment." (PMID 28409160, 2017). "Defective muscle perfusion in older subjects with diabetes or pre-diabetes is likely the effect of the combination of reduced muscle mass and anabolic insulin resistant state leading to impairment of microvascular function." (PMID 29131837, 2017).
diabetes (continued). "Type 2 diabetes mellitus (T2D), which accounts for about 90% of diabetes cases, is a complex metabolic disorder characterised by chronic hyperglycemia due to decreased insulin action and increased pancreatic beta- (β-) cell dysfunction." (PMID 28529949, 2017). "Dysregulation of the insulin/IGF system has major implications for several pathological conditions such as diabetes and cancer." (PMID 28880250, 2017). "The association between proximal humerus fractures and type 2 diabetes (T2DM) is unclear and some studies point to insulin treatment, hypoglycaemic episodes consequently to inadequate control of diabetes or, more recently, to an alteration of trabecular bone." (PMID 29228945, 2017). "In our study, ADAMTS13 activity was associated with an increased risk of incident diabetes, even after adjustment for other known risk factors, including VWF antigen, fasting glucose and fasting insulin levels." (PMID 27787621, 2017). "Diabetes is a progressive metabolic disorder with defects in insulin secretion from the beta cells and/or insulin resistance in peripheral tissues leading to chronic hyperglycaemia representing type 1 and type 2 diabetes, respectively." (PMID 28713837, 2017). "Oleanolic acid has been used as therapeutic agent in models of diabetes to improve insulin action, inhibit gluconeogenesis and promote glucose utilization." (PMID 29137205, 2017). "Type 1 diabetes mellitus (DM) is an autoimmune disease in which T-lymphocytes attack insulin-producing beta cells in the pancreas." (PMID 28986401, 2017). "Last, the era since 1987 was marked by the monumental efforts to develop insulin inhalers for noninvasive treatment of diabetes." (PMID 27748638, 2017). "Elevated insulin level is frequently observed in type 2 diabetes, which makes up ∼90% of cases of diabetes." (PMID 28521289, 2017). "Diabetes mellitus (DM) is a group of frequent metabolic disorders characterized by abnormalities in insulin secretion and/or insulin action." (PMID 29464184, 2017). "Glycemia was higher in DM compared to CT (p < 0.001), whereas serum insulin levels were lower in DM (p < 0.01), confirming the effectiveness of the diabetes induction procedure." (PMID 28781721, 2017). "Four of these studies represent common drug classes for glucose-lowering medication in diabetes: basal insulin, GLP-1 RAs and SGLT-2 inhibitors." (PMID 29020969, 2017). "The odds of both mild anemia and moderate/severe anemia compared to no anemia is highest in the oldest age group (≥ 70 years), female gender, higher ASA-PS scores (4 & 5), diabetes mellitus on insulin, congestive heart failure and grade 4 or 5 kidney disease." (PMID 28777814, 2017). "Hypoglycemia is a common adverse effect of management for diabetes, especially insulin therapy, and a barrier to optimal glycemic control." (PMID 28067320, 2017). "As hepatic aPKC can also be activated by ceramide, which is relevant in diabetes development, the prediction of the presence of an insulin induced bistable aPKC switch should be first tested in situations where ceramide levels are low." (PMID 29118381, 2017). "In the case of diabetes exogenous insulin can be brought into the blood circulation in order to maintain a safe blood glucose level." (PMID 28060898, 2017). "Until the middle of the last century, there was little distinction in the treatment of diabetes mellitus among people with different ages or phenotypic characteristics because only insulin was available." (PMID 29152218, 2017). "In diabetes, the inability of β-cells to secrete adequate amounts of insulin leads to the development of hyperglycemia." (PMID 28303894, 2017). "Diabetes develops when the compensatory growth of pancreatic β cells is insufficient to produce an appropriate amount of insulin, which can overcome insulin resistance." (PMID 28646158, 2017).
diabetes (continued). "Here, we explored the immune responses by investigating the change of the peripheral T-cell subsets after AHSCT and traditional insulin injection in patients with type 1 diabetes mellitus." (PMID 28420440, 2017). "In adulthood, autoimmune diabetes can present as non-insulin-requiring diabetes, termed as ‘latent autoimmune diabetes in adults’ (LADA)." (PMID 28438156, 2017). "Optimizing insulin therapy and achieving good metabolic control is still a challenge in the management of type 1 diabetes mellitus (T1DM)." (PMID 29162560, 2017). "These analyses showed that LADA subjects with DR who were treated with insulin showed a lower QoL than any other combination of diabetes type, insulin treatment and DR." (PMID 29062603, 2017). "Rosiglitazone is a thiazolidinedione (TZD) insulin sensitizer, which has been shown to favorably influence pancreatic beta cell survival and function in rodent models of diabetes." (PMID 28640857, 2017). "Transgenic pigs expressing the mutant insulin C94Y are a model for permanent neonatal diabetes, now termed mutant INS gene-induced diabetes of youth (MIDY)." (PMID 28752056, 2017). "Diabetes progress and impaired insulin action are accompanied with pathochanges at multiple tissues, including the pancreas, skeletal muscles, the liver and adipose." (PMID 28117714, 2017). "Nevertheless, we believe giving more weight to the early values taken before the universal introduction of intensive insulin-treatment, better reflects the full duration of diabetes." (PMID 28510594, 2017). "For example, studies have demonstrated positive relationships between the education levels of Nigerian diabetes patients’ and their knowledge about diabetes and its management, and the appropriate use of insulin." (PMID 28045979, 2017). "The experimental setting of an induced hypoglycemia mimics an acute complication in patients with diabetes mellitus (both type 1 and type 2), which results from an overdose of insulin, some other antidiabetic drugs or stress." (PMID 29077038, 2017). "Although healthcare providers can assist in advising on how to make adjustments in insulin doses and so forth in order to balance the juggling of blood glucose, peers with diabetes are more likely to help prioritize the dual role in early motherhood." (PMID 29092688, 2017). "The benefit was partially attributed to amelioration of impaired insulin secretion and liver and kidney function in diabetes." (PMID 28954411, 2017). "Meta-analysis results are consistent with those of a previous meta-analysis, which reported that resveratrol consumption significantly reduced the fasting glucose and insulin levels, and reversed insulin resistance among participants with diabetes." (PMID 29018489, 2017). "They compare ghrelin resistance to insulin resistance in type 2 diabetes mellitus, which is overcome by using high doses of insulin." (PMID 28298897, 2017). "We demonstrated that the WB sensitivity of insulin and the other peptide hormones involved in diabetes was improved by the addition of extra steps to the general WB procedure." (PMID 28761041, 2017). "Undercarboxylated osteocalcin increases insulin sensitivity and secretion, and serum levels of undercarboxylated osteocalcin negatively correlate with insulin resistance, obesity, and diabetes." (PMID 28695134, 2017). "This gap in PCPs’ competence to treat diabetes with insulin contributes to the problem known as clinical inertia, “the failure to advance therapy when indicated,” resulting in underuse of insulin and poor glycemic control." (PMID 28279950, 2017). "In contrast, long term netrin-1 treatment in mice showed a preventive role against high-fat diet/STZ-induced diabetes through maintained islet insulin secretion and reduction of vascular inflammation." (PMID 29059224, 2017).